CD44 (CD44 molecule (IN blood group))
Diseases named in the same sentence as CD44 in open-access papers (continued):
Sharing a sentence is not in itself a finding about the gene and the disease.
tumor (continued). "Simultaneously, the expression of CSC markers in the tumour tissues were enhanced by 30-, 150- 200-folds for CD24, CD133 and CD44, respectively, when compared to miPSCs." (PMID 32203212, 2020). "Most scholars believe that CD44 + CD24-/low cells represent interstitial breast CSCs, which are mainly distributed in the edge of tumor invasion." (PMID 33282946, 2020). "PD-L1 expression has been shown to correlate with the cancer stem cell (CSC)-like characteristics including the expression of CD44 and/or CD133 at high levels on tumor cells." (PMID 33193345, 2020). "CSC-marker CD44 is known to mediate cancer cell survival, proliferation, and motility, as well as the modulation of tumor microenvironment, indicating CD133 and CD44 as an excellent marker set to validate a CCSC-like-phenotype." (PMID 32927768, 2020). "These tumor-initiating cells have been reported in the literature through specific surface proteins, such as CD133, CD166, or CD44, which on average account for 11.4% of epithelial cells in primary CRC." (PMID 32722130, 2020). "IHC staining of CD44 and EMT-related markers (Twist, ZEB1 and E-cad) in tumor tissues was implemented." (PMID 32497020, 2020). "The combination group showed significantly greater tumor reduction 17, 28, and 31 days after NIR-PIT compared to CD44-targeted NIR-PIT group (p < 0.05, Tukey–Kramer test)." (PMID 32927646, 2020). "The range of CD44 expression in primary SCCOHT tumors was more dynamic than with Claudin-4, shown by select tumor cores that moderately expressed CD44 (range of CD44/DAPI in SCCOHT = 0.22–31.9%)." (PMID 33355532, 2020). "The expression of the activation markers CD69 and CD44 was substantially upregulated on CD4+ and CD8+ tumor-infiltrating T cells in M1-treated mice, indicating the reinvigoration of T-cell populations." (PMID 33311488, 2020). "Protein expression was quantitated using the Image J software for those markers and showed that approximately 50% of tumour sections expressed AFP and CK19 while for GPC3 it was 20% and for CD44 it was 30%." (PMID 32203212, 2020). "Tumor infiltrating innate lymphoid cells (ILCs) can show an activated phenotype (expression of CD69, CD44, MHCII, and KLRG1) and provide tumor immunosurveillance." (PMID 33266109, 2020). "Three syngeneic mouse tumor models, MC38-luc, LL/2, and MOC1, underwent combined CD44-targeted NIR-PIT and short-term IL-15 administration with appropriate controls." (PMID 32927646, 2020). "Since CD44-targeted NIR-PIT showed an effective therapeutic response in a MOC2-luc tumor, we analyzed the tumor infiltration of CD8+ T cells before and after CD44-targeted NIR-PIT." (PMID 33322807, 2020). "We also identified three CD8 T cell subsets: exhausted CD8 (CD39+ Tim3+ Lag3+ CD8+), classical CD8 (CD3+ CD8+ CD44+ MHCII+ Tim3− Lag3− CD25−) and tumor-reactive CD8 (CD39+ CD103+ CD8+)." (PMID 32764562, 2020). "After entering the blood circulation, HA-DOP-Cu-MP accumulates in the loose tumor tissue through the EPR effect, and then HA-DOP-Cu-MP can be internalized by tumour cells through CD44-mediated endocytosis." (PMID 32423174, 2020). "Our previous study showed MOC1 tumor has low and more heterogeneous CD44 expression and CD44-targeted NIR-PIT was less effective against this type of tumor." (PMID 32927646, 2020). "It was interesting to detect differences in CD44, ALDH1 protein and STAT3 gene expression between the UWG02CTC and UWG02ASC, which probably reflects the different pathways of tumour cell dissemination." (PMID 31953491, 2020). "In fact, as previously reported, HA of various MW interact with its two major cell surface receptors, CD44 and RHAMM that act independently or as co-receptors to trigger downstream signaling which enhances tumor progression." (PMID 32708202, 2020).
tumor (continued). "The results showed that tumor-free cell DNA was able to alter the gene expression of MMP9 and CD44, alter the expression profile of nine miRNAs, and increased the tryptophan consumption and cell migration rates in non-tumor cells." (PMID 33303880, 2020). "As expected, both Omomyc IBs and GFP control IBs were internalized into CD44+ TNBC cells in vitro through an endosomal route, but only Omomyc IBs had a cytotoxic effect on tumor cells." (PMID 32260326, 2020). "Total counts of CD44+ CD8+ T and NK cells in tumors, tumor-draining lymph nodes (TDLNs), and spleens were similarly increased in hIL-2/NARA1 complex- and NARA1leukin-treated animals." (PMID 33353953, 2020). "Flow-cytometric analysis revealed an increase in the expression of IL-10R (CD210) in Lin-thy1.2+CD25+CD44+ DN2 T-cells isolated from the thymus of tumor-bearing vs. control, tumor-free mice." (PMID 32582141, 2020). "Traditional gating of antigen-experienced CD44+ CD8+ cells, the fraction containing tumor-specific T cells, was then performed." (PMID 33329575, 2020). "A central player in the tumor microenvironment proved to be the CSCs which can be marked by CD133, CD44, CD90, EpCAM, and CD105." (PMID 31781608, 2019). "To further detect the roles of CD44 and CTTN in RNF128-induced tumor progression, we interfered CD44 or CTTN expression in M14-shRNF128 cells to determine the changes in cellular EMT and stemness." (PMID 30832692, 2019). "Blockade of IL-6/STAT3 signaling attenuated the expression of CD44, CSC-like properties, and aggressive tumor behavior in vitro and in vivo." (PMID 31315262, 2019). "Many researchers have found that cells induced to undergo EMT can gain cancer stem cell (CSC) properties, with the enrichment of a CD44(+)/CD24(−) subpopulation, which is responsible for tumour initiation and formation." (PMID 31684910, 2019). "Deletion of Dll1 in DCs also had a significant effect on CD8+ T-cells that resulted in their decreased activation in the tumor as shown by decreased expression of CD25 and CD44." (PMID 30940183, 2019). "The ability of α‐Mangostin to inhibit pancreatic CSC markers CD24, CD44 and CD133 demonstrate that it can modulate the tumour growth by the suppression of the CSC population." (PMID 30712329, 2019). "Horst and colleagues investigated the expression of CD44, CD133 and CD166 in 110 CRC patient tumours by IHC and found 33%, 52% and 64% of the cases positive respectively." (PMID 30899442, 2019). "As already alluded above, CSCs within the OSCC tumor nests co-express OCT4, SOX2, NANOG, phosphorylated STAT3 (pSTAT3), CD133, CD44, and c-MYC." (PMID 31861233, 2019). "In order to study the effect of MSCs on Tumor Cell marker flow cytometry analysis were performed on CD24 and CD44." (PMID 31351482, 2019). "Emerging evidence has demonstrated that CD44 plays an important role in regulating the EMT and angiogenesis processes, which contribute to tumor initiation and progression." (PMID 31528214, 2019). "As shown by double immunofluorescence analysis with anti-EpCAM, anti-CD44, and anti-human CD133/1 antibodies, we observed that SDC1 was accumulated in tumor cells with CSC properties." (PMID 31443604, 2019). "Stem cell relative marker CD44, CD90, and CD105 and tumor marker CA9 and osteopontin (OPN) expression were quantified using RT-qPCR." (PMID 31640774, 2019). "CSCs are also regarded as the seeds for therapeutic resistance, tumor recurrence and metastasis, and are recognized by a number of defined markers, such as they are positive for CD133 and CD44, and express high levels of integrin alpha2beta1." (PMID 30728896, 2019). "MEDI9197 induced an increase in total effector T cells (ratio of Teff (CD45+/TCRβ+/CD44+/CD62L−) to Tnaive/CM (CD45+/TCRβ+/CD44+/−/CD62L+) and effector CD8+ T cells (ratio of CD45+/TCRβ+/CD8α+/CD44+/CD62L− to Tnaive/CM) in the tumor 6–8 days after dosing." (PMID 31511088, 2019).
tumor (continued). "A recent study showed that presence of the IL-6 superfamily member, oncostatin-M (OM) in the TME upregulates genes related to the CSC phenotype such as SNAIL and CD44 in TNBC cells lines, leading to enhanced tumor formation in vivo." (PMID 31450577, 2019). "We further analysed for mRNA levels of CD133, CD44, OCT4, SOX2 and BMI1, in tumour and distal margin tissues compared to the matched normal tissues expression using real‐time PCR." (PMID 30950180, 2019). "The enhanced efficacy was associated with the increased CD8 + T cell, increased effector memory T cells (CD44 + CD8 + CD62L+), decreased Treg (CD4 + CD25 + Foxp3+) and M2 macrophages (F4/80 + CD206+) in the tumor microenvironment." (PMID 31882868, 2019). "AC009 also reduced cancer stem-cell marker CD44+/CD24+ expression and restored the tumor inhibition effect of cetuximab in KRAS-mutant CRC." (PMID 31717759, 2019). "The lysosomal localization of CD44 aptamers is supported by an earlier study as well, where LRP-1 protein facilitated lysosomal localization of CD44 receptor in tumor cells." (PMID 31080896, 2019). "Next, we looked at expression of several common surface markers involved in tumor-immune recognition (MHC class I, CD1d, PD-L1) as well as tumor cell migration and invasion (CD44)." (PMID 31139180, 2019). "The expression of stem cell‐related markers, including CD44, Oct‐4A, Sox2 and c‐Myc, was also up‐regulated in CL141 tumour sphere cells." (PMID 31638335, 2019). "HCT116, with CD44+–CD133+ - cells are found to be proliferative compared to CD44low CD133low cells, and are high in in vivo xenograft tumor formation." (PMID 31337825, 2019). "Consistent with the migration assay findings, CD133, CD44, and ALDH1 protein expression in tumor control culture cells was moderate." (PMID 30917533, 2019). "HA/CD44-activated lncRNA UCA1 also downregulates miR-145 expression and stimulates ROCK expression required for cytoskeletal activation and tumor cell motility (e.g., migration and invasion)." (PMID 31293964, 2019). "Normal fibroblasts from 4T1 tumor-bearing mice showed the same expression patterns as CT26.WT-NFs for the markers CD39, CD87, CD44, and CD49b." (PMID 31428583, 2019). "The mRNA expression of the putative tumor stem cell markers SOX2, Nanog, CD44, ALDH1, c-myc, and Oct4 was analyzed by qPCR." (PMID 30539198, 2019). "Inspection of the PCA loadings identified the cell-cell interaction component and the environmental component for a subset of proteins (including CD20 and CD44) as the most informative SVCA features for PC1, which correlates with tumor grade." (PMID 31577949, 2019). "Our current studies focus on identifying the molecular mechanisms involved in the regulation of SOX2 by CD44 signaling and the role of CD44‐SOX2‐SNAIL/SLUG axis in eliciting EMT and migration/tumor progression." (PMID 30206982, 2019). "Resected tumor samples from five ovarian HGSC were subjected to spheroid culture, and cell surface protein CD117 and CD44 were identified as tumor-initiating cell markers." (PMID 31130643, 2019). "On the other hand, comprehensive functional experiments are needed: eg it will be interesting to select CD44+/CD133+/ITGA6+/CD36+ cells and to evaluate their tumor formation capacity in NOD‐SCID mice brains." (PMID 30467961, 2019). "Compared with the shRNA control, TRIM59 knockdown decreased expression of p-STAT3, proliferation marker Ki-67, and cancer cell stemness marker CD44, whereas the levels of mH2A1 was elevated in GSC xenograft tumor tissues by immunohistochemical (IHC) analyses." (PMID 31488827, 2019). "In this study, we have evaluated the association between the co-expression of putative CSC markers CD44, CD133, which have been shown to identify cells with tumour initiating and progression properties." (PMID 30899442, 2019).
tumor (continued). "CD133high or CD44+CD24- cells or CD133+CD44+ cells have been isolated from DU145 and PC3 cell lines and have been shown to be able of inducing colony tumor formation in vitro and tumor formation in vivo after subcutaneous injection in mice." (PMID 31366128, 2019). "The main factors that correlate with the embryonic mesenchymal state, tumor metastases and progression include HLA-G, HSP70, hypoxia, STAT3, CD44, SNAIL1, TWIST1, PRRX1, TGFb, WNT/bCAT, ID, and MMPs." (PMID 30899759, 2019). "A tumor sphere formation assay was carried out, and the levels of a panel of established CSC markers, including CD133 and CD44, were analyzed." (PMID 31559140, 2019). "The different phenotype, based on CD44 gene expression in PC3 and DU145 cells, was confirmed by a different response to IL-4, a regulator of basal-like cells showing characteristics of tumor-initiating cells by inducing expression of CD44." (PMID 30754655, 2019). "The downregulation of HYAL1 correlated with reduced CD44 and RHAMM expression, and PI3K/AKT signaling, suggesting a feedback mechanism between HA degradation and signaling in tumor cells." (PMID 31134064, 2019). "Previous published work has shown that CD44 and MMP-9 co-localize in tumor cells at the invasive front." (PMID 31579438, 2019). "Thus, CD44 isoforms may be used as an important tumor marker for the detection of CSCs." (PMID 31293964, 2019). "We observed that CD44 and ALDH1 were also expressed by macrophages, and we therefore conducted IHC studies using CD68 to specifically identify the proportion of tumor macrophages." (PMID 30999901, 2019). "Some CD44+ CSCs have epithelial–mesenchymal transition (EMT) ability, and contribute to tumor progression and metastasis." (PMID 30992079, 2019). "Our study highlights an interaction among CD8+ T cells infiltration, PD-L1 expression, and CD44+/CD133+ CSCs existence, thus providing a rationale for designing ideal combination cancer therapies based on tumor immunology." (PMID 30991694, 2019). "Understanding the relationship between the CD44 and PROCR genes allows for a better clonal reconstruction of the overall heterogeneous tumor and for the identification of ultra-precision therapy." (PMID 31379741, 2019). "Deficiency in DLL1 expression in DCs resulted in a significant reduction of CD8+ T-cell activation, tumor antigen-specific CTL and differentiation of central memory CD8+CD44+CD62L+ T-cell populations." (PMID 30940183, 2019). "Immunohistochemistry study revealed that tumour specimens from both oral cavity and peritoneum were negative for tumour necrosis factor alpha and CD24 but positive for CD44 and CD36." (PMID 31645882, 2019). "Localization of MMP-9 on the surface of keratinocytes depends on its interaction with CD44 which activates transforming growth factor-β (TGF-β), and is essential for the promotion of tumor invasion and angiogenesis." (PMID 31579438, 2019). "Similar effects of KYA1797K on the specificities in the suppression of the expression of β-catenin and pan-RAS as well as CD44 and ALDH1A3 were confirmed by IHC analyses of the PDX tumor tissues." (PMID 30965636, 2019). "Other authors highlighted that ALDH-1 is a marker of invasiveness and metastatic potential, while the CD44+/CD24− ratio indicates mainly a “self-renewal” capacity, thus these two markers are assigned different functions during the tumor progression." (PMID 31330794, 2019). "1, MUC-1), etc., CTSC surface markers include CD26, CD44, CD133 and CXC chemokine receptor 4 (CXCR4), etc., circulating EMT positive tumor cell surface markers are vimentin, fibronectin, calcium adhesion protein-N and calcium adhesion protein-O and so on." (PMID 31767014, 2019). "CSC markers included CD24, CD44, and SNAIL; CSC properties included tumor sphere formation, migratory capacity, and tumor initiation." (PMID 31036052, 2019).
tumor (continued). "Due to the increased levels of CTCs (CD44+CD24−) in the blood of the animals in the obASC-PDX group, the expression of CD44 in tumor sections was analyzed using immunohistochemistry." (PMID 31118047, 2019). "si-hVDAC1 tumor treatment markedly decreased the expression of CSCs markers, such as CD133, SOX2, KLF4, Nestin, and CD44, as evaluated by quantitative immunoblotting and qRT-PCR." (PMID 31661894, 2019). "Our previous work has shown that pancreatic CSCs identified by CD44+/CD133+ expression had the ability to form tumorspheres, along with chemotherapeutic drug resistance and tumor-formation ability." (PMID 30991694, 2019). "By using double IHC, we found that pSTAT3 positive tumor cells co-expressed the basal markers CK5/6, CK14 as well as CD44." (PMID 31438567, 2019). "CD44 is known as common CSC marker and considered critically related with the migration and adhesion of CSCs and during the formation of tumor tissue." (PMID 30818864, 2019). "By contrast, HPPDC nanoparticles exhibited a much higher inhibitory effect on the MDR1 and COX-2 expressions due to their efficient tumor-accumulation via the EPR effect and CD44-mediated active tumor targeting." (PMID 31623608, 2019). "We also examined the expression levels of JUP (gene for plakoglobin), CD44, and PAK2 in CTCcl+ vs. CTCcl− TNBC PDX models as they were reported to have a role in tumor cell aggregation/CTCcl formation and subsequent metastasis." (PMID 31652963, 2019). "CD44 is considered a marker for GBM CSCs, reinforcing the idea that OOS affects GBM1 tumor growth by impairing CSCs." (PMID 31467641, 2019). "In comparison, tumor-specific CD8+ T cells in spleens, DLN and NDLN largely maintained IL-7R expression despite CD44 upregulation, and upregulation of CD69 was observed predominantly within the DLN." (PMID 31998326, 2019). "Immunohistochemistry gradings for 5 biomarkers (CD44, ABCC4, ABCC11, N-Cadherin and pan-Cadherins) and 3 clinical parameters (tumor size, tumor grade and node status) of 298 patient cohort were used to develop a machine learning based statistical algorithm." (PMID 30894144, 2019). "To confirm this result, we further analyzed the expression of thymidine kinase 1 (TK-1) or CD44 isoforms in our system, as TK-1 is known to be a tumor proliferation marker, and ESRP1 is known to regulate CD44 isoform switching during the EMT." (PMID 31362365, 2019). "In contrast to GLUT1 and CD44 expression, a decreased frequency of HKII and LDHV expression in tumor samples, compared to normal testicular samples, was observed in the present study." (PMID 31316469, 2019). "In this research, CD44-targeted, biotin-targeted, and folate-targeted amphiphilic Bio-oHA-Hyd-FA drug carriers were successfully synthesized for delivery of ICA&Cur to tumor cells and cancer stem cell." (PMID 31571501, 2019). "Of note, Rho GTPase-mediated recruitment of CD44 to the cell membrane by NGF-TrkA further contributes to CSCs stemness maintenance and survival, resulting in higher tumor aggressiveness." (PMID 31812953, 2019). "The over-expression of CD44+ and CD133+ cells provides resistance in tumours and the capability for disease relapse after chemo/radiotherapy in immunodeficient mice." (PMID 30875950, 2019). "Blockade of CD44 by a neutralizing antibody induced apoptosis of CD90-positive cells and prevented tumor formation in mice." (PMID 31547062, 2019). "In a recent study, intercellular CD44 homophilic interactions and its subsequent interactions with PAK2 were reported to mediate tumor cell aggregation and polyclonal metastasis in BC PDX models." (PMID 31652963, 2019). "To deeply investigate the relationship between markers gene expression levels and tumor grade, we analyzed the mRNA expression levels of Survivin, CK19, CK20, CD44 and E-Cadherin genes in BCs G1, G2 and G3." (PMID 30650148, 2019).